CASR (calcium sensing receptor)
Diseases named in the same sentence as CASR in open-access papers (continued):
Sharing a sentence is not in itself a finding about the gene and the disease.
hyperparathyroidism (71 papers, 2008 to 2026). Hyperfunction of the parathyroid glands resulting in the overproduction of parathyroid hormone. "Aging, vitamin D deficiency, and hereditary reduction of CaSR expression/activity are causally linked to hyperparathyroidism, but how these conditions alter PTH secretory dynamics has not been fully characterized." (PMID 40492090, 2025). "In cases of 2 nonfunctional CaSR alleles or mutations that result in severely reduced CaSR activity, the phenotype is more severe and is referred to as neonatal severe hyperparathyroidism." (PMID 35299844, 2021). "A CaSR genetic mutation, causing neonatal severe hyperparathyroidism (NSHTP), was associated with a paucity of deep white matter and a delayed myelination in a six-month-old infant." (PMID 31336912, 2019). "Alterations of CaSR expression have been implicated not only in hyperparathyroidism but also other neoplasms." (PMID 27679579, 2016). "In the chronic use of lithium, due to the increase in the set point of the calcium sensing receptor, hyperparathyroidism is observed with an absolute risk of 10% (versus 0.1% of the general population)." (PMID 26604931, 2015). "Additional studies on phenotypical and histological traits will help to discriminate between the different effects of each point mutation on the severity of hyperparathyroidism and concomitantly to improve our understanding of CASR mutations in human patients." (PMID 22527485, 2012). "In summary, this report describes a case of neonatal FHH secondary to a heterozygous inactivating missense mutation within the CaSR gene that presented with severe hyperparathyroidism, overt neonatal skeletal demineralization and perinatal fractures." (PMID 22620673, 2012). "Homozygous or heterozygous mutations in CaSR (Calcium Sensing Receptor) gene are the source of NSHPT (neonatal severe hyperparathyroidism) and FHH (familial hypercalcemic hypercalciuric), respectively." (PMID 22567348, 2011). "In addition, association between VDR and CaSR were also confirmed in patients with hyperparathyroidism (p = 0.000)." (PMID 42314434, 2026). "Neonates with FHH based on paternally inherited CaSR mutations may present with or develop symptomatic hyperparathyroidism and fractures." (PMID 34659108, 2021). "While it is known that homozygous mutations in CaSR may lead to life-threatening forms of neonatal severe hyperparathyroidism (NSHPT), few reports have described a severe clinical course in neonates with FHH due to heterozygous mutations." (PMID 34659108, 2021). "Bi-allelic CaSR mutations typically lead to neonatal severe hyperparathyroidism (NSHPT)." (PMID 32120468, 2019). "Besides the mutations of the genes involved in types 2 and 3 FHH, FHH syndromes related to a mutation of the CASR gene must be differentiated from hyperparathyroidism with normal PTH." (PMID 28122587, 2017). "Moreover, the R990G variant of CaSR seems to be more common in the general Chinese population, but also in Chinese patients with hyperparathyroidism." (PMID 28122587, 2017). "Herein, we present the case of a newborn girl with a novel heterozygous inactivating mutation of the CaSR gene, severe hyperparathyroidism, overt skeletal demineralization, and perinatal fractures who was treated with cholecalciferol to moderate her clinical course." (PMID 22620673, 2012). "Thus, DGKδ-associated perturbations of CaSR signal transduction may have intracellular and tissue-specific effects that mirror CaSR loss-of-function variants associated with hyperparathyroidism phenotypes." (PMID 40372791, 2025). "Blocking aberrant signaling through Aβ, the GABAB1R/CaSR dimer, and Tau can suppress tonic PTH hypersecretion in hyperparathyroidism associated with vitamin D deficiency." (PMID 40492090, 2025). "The calcium-sensing receptor (CaSR) is a validated therapeutic target in the treatment of hyperparathyroidism and related diseases." (PMID 40141226, 2025).
hyperparathyroidism (continued). "Another class of drugs used to treat hyperphosphatemia and hyperparathyroidism are calcimimetics, including Cinacalcet, which acts by allosterically activating the calcium-sensing receptor (CaSR)." (PMID 38672265, 2024). "Hypocalciuric hypercalcemia type 1 (OMIM phenotype number 145980) is an AD condition resulting from an inactivating variant in CASR, resulting in lifelong mild to moderate hypercalcemia, inappropriate hypocalciuria, and normal PTH to mild hyperparathyroidism." (PMID 38606357, 2024). "A statistically significant decrease in the frequency of detection of normal expression of CaSR and VDR receptors occurs in any morphological variant of hyperparathyroidism and is observed in 93–60% of drugs." (PMID 37448244, 2023). "Our advantage is to explore the clues of the pathogenesis of hyperparathyroidism by studying the expression difference of CaSR in hyperparathyroidism." (PMID 36755240, 2023). "The expression of CaSR, VDR and its relationship with the main laboratory parameters, the clinical variant of hyperparathyroidism, and the morphological substrate were studied." (PMID 37448244, 2023). "Inactivating variants in CASR cause numerous hypercalcaemic disorders of differing severity, including FHH and neonatal severe hyperparathyroidism, through a loss-of-function mechanism." (PMID 35869530, 2022). "It would be interesting to expand these clinical case studies, paying particular attention to the interactions between NKCC2 and CASR (extracellular calcium-sensing receptor) (the molecular target of drugs for hyperparathyroidism)." (PMID 34768847, 2021). "The FDA-approved drug cinacalcet is an allosteric activator of CaSR used for treatment of hyperparathyroidism." (PMID 33400691, 2021). "Genetic evaluation was redone, adding sequencing of other genes associated with hyperparathyroidism (AP2S1, CASR, CDC73, CDKN1B, GNA11, MEN1 and RET) including screening for mosaicism." (PMID 34556169, 2021). "The diagnoses used in drug treatments that target CASR are hyperparathyroidism, bone destruction, chronic kidney disease with secondary hyperparathyroidism and impaired renal function." (PMID 29545597, 2018). "In an in vivo murine model of primary hyperparathyroidism in which cyclin D1 overexpression is targeted to the parathyroid, expression of the CaSR in the gland is markedly reduced and correlates with the severity of the hyperparathyroidism." (PMID 27679579, 2016). "Concurrent deletion of the CaSR with parathyroid hormone gene corrected for the effects of hyperparathyroidism, hypercalcemia, hypophosphatemia, and whole-body growth retardation." (PMID 27303307, 2016). "The biochemical basis of Cinacalcet's efficacy in treating hyperparathyroidism with minimal side effects is likely achieved by the extremely high level of expression of the CaSR in the adult parathyroid gland." (PMID 27303307, 2016). "The development of the drug Cinacalcet to treat hyperparathyroidism was based on the ability of the CaSR to suppress parathyroid hormone release from the parathyroid gland." (PMID 27303307, 2016). "Even in the CaSR hypoexpression state induced by severe hyperparathyroidism, the resistance to CaSR activation was overcome by increasing the dose of cinacalcet HCl." (PMID 21461394, 2011). "Indeed, metabolic acidosis rapidly inhibits the CaSR that causes PTH release and relative hyperparathyroidism." (PMID 33911128, 2021). "The elevated iCa and corresponding normal PTH of this family member confirmed the pathogenicity of the CASR variant leading to elevated iCa without hyperparathyroidism." (PMID 34556169, 2021). "To date, reports have shown that more than 10% of patients with hyperparathyroidism may have a germline mutation involving the MEN1, RET, cell division cycle 73 (CDC73), calcium-sensing receptor (CASR), cyclin-dependent kinase inhibitor (CDNK1B), or PTH genes." (PMID 29983117, 2018).
hyperparathyroidism (continued). "These drugs are capable of making CaSR more sensitive to serum calcium levels, thereby decreasing the parathyroid hormone and the serum calcium in hyperparathyroidism, whether they are primary, secondary or neoplastic." (PMID 28122587, 2017). "Two drugs have been launched: Sensipar/Mimpra cinacalcet (Amgen/NPS) is a PAM of calcium-sensing receptor (CaSR) for hyperparathyroidism treatment; Selzentry/Celsentri maraviroc (Pfizer) is a NAM of C-C chemokine receptor type 5 (CCR5) for human immunodeficiency virus (HIV) therapy." (PMID 27047374, 2016). "Univariate subgroup analyses that excluded patients with diabetes, hyperparathyroidism or hyperphosphataemia, as these factors are key determinants of vascular calcification, also did not reveal any association between CASR SNPs and AoC or CAC scores." (PMID 25786244, 2015). "This agent activates the CaSR through binding to the seven transmembrane domain of the CaSR and has been shown to improve the sensitivity of the parathyroid glands to calcium and to treat hyperparathyroidism." (PMID 22620673, 2012). "Furthermore, TDF was shown to inhibit the activity of calcium-sensing receptors, CaSR, in a dose-dependent manner and may, in part, explain that TDF-mediated hyperparathyroidism may be promoted by the direct effect of the drug on CaSR." (PMID 41295288, 2025). "Inactivation of CaSR in the parathyroid gland leads to stimulation of PTH release and subsequent hyperparathyroidism." (PMID 38606357, 2024). "Cinacalcet HCl (cinacalcet), an allosteric modulator of CaSR that increases the sensitivity of the CaSR to extracellular calcium, suppresses PTH secretion in patients with hyperparathyroidism." (PMID 36306782, 2022). "Lithium-induced hyperparathyroidism can be due to lithium’s action on the calcium-sensing receptor and GSK-3, revealed by unmasking hyperparathyroidism in patients with a subclinical parathyroid adenoma or possibly by initiating multiglandular hyperparathyroidism." (PMID 36678571, 2023). "Decreased calcium-sensing receptor (CaSR) has been observed in hyperparathyroidism (HPT) without a known mechanism." (PMID 36755240, 2023). "For example, calcimimetics (CaSR activators) are used to treat hyperparathyroidism while negative allosteric modulators (calcilytics, e.g., NPS2143) target genetic hypocalcemia disorders." (PMID 33790802, 2021). "Likewise, weekly administration of an Aβ42-neutralizing antibody suppressed tonic PTH hypersecretion and synergized with daily administration of cinacalcet, a calcimimetic that activates CaSR homodimers, to reduce serum PTH levels in aging-induced hyperparathyroidism (HPT) mice." (PMID 40492090, 2025). "The spectrum of hyperparathyroidism with high serum calcium and yet normal PTH levels is not extensively defined and may involve calcium-sensing receptor variations." (PMID 40709988, 2025).
hypoparathyroidism (52 papers, 2006 to 2026). Hypoparathyroidism is an endocrine disorder in which the parathyroid glands in the neck do not produce enough parathyroid hormone (PTH). "Autosomal-dominant hypocalcemia type 1 (ADH1; MIM: 601198) is a rare genetic form of hypoparathyroidism caused by gain-of-function (GoF) variants in the calcium-sensing receptor (CaSR) encoded by CASR (MIM: 601199)." (PMID 40664210, 2025). "The differential diagnoses in this case included primary hypoparathyroidism, Bartter syndrome type 5 (CaSR (calcium-sensing receptor) mutation), Gitelman syndrome, and claudin mutations." (PMID 40454415, 2025). "For example, anti-acetylcholine receptor antibodies have been reported to increase in patients with ICI-associated myasthenia gravis, and anti-calcium-sensing receptor antibodies to increase in patients with ICI-associated hypoparathyroidism." (PMID 41404503, 2025). "The majority of our isolated hypoparathyroidism cases harbored heterozygous CASR mutations, including V836L and the novel V836I variant." (PMID 41155848, 2025). "As an acquired disease analogous to ADH1, acquired hypoparathyroidism, including immune-checkpoint inhibitor-related hypoparathyroidism, has been reported to be caused by activating autoantibodies against CaSR." (PMID 36099030, 2022). "Upregulating mutations of the CaSR have been manifest as hypocalcemia, hypoparathyroidism, and urinary calcium wasting." (PMID 30071694, 2018). "Such problematic management is typically observed in such disorders as APS type 1, hypoparathyroidism associated with malabsorption (especially celiac disease), and activating mutations of the calcium sensing receptor (CaSR)." (PMID 27384692, 2017). "The mirror image of FHH, autosomal-dominant hypocalcemia (ADH) type 1, is caused by activating mutations in the CASR and is the most common genetic form of isolated hypoparathyroidism." (PMID 27803672, 2016). "For example, autoantibodies against calcium-sensing receptor are found in almost all APECED patients with hypoparathyroidism, whereas anti-NALP5 antibodies, also linked to hypoparathyroidism, are much less common." (PMID 24109480, 2013). "We identified 2 CASR mutations in 3 cases with isolated hypoparathyroidism." (PMID 41155848, 2025). "Additionally, specific genetic mutations, particularly those affecting the calcium-sensing receptor (CaSR), can increase susceptibility to hypoparathyroidism." (PMID 39258042, 2024). "Autosomal dominant hypocalcemia type 1 (ADH1) is a rare form of hypoparathyroidism that is characterized by gain-of-function mutations in the CASR gene, which provides instructions for producing the protein called calcium-sensing receptor (CaSR)." (PMID 37371242, 2023). "Interestingly, considering autoimmunity as an important cause of hypoparathyroidism, the evaluation of calcium-sensing receptor (CaSR)-activating autoantibodies has been performed, resulting in elevated autoantibodies levels." (PMID 36672478, 2023). "The etiology of hypoparathyroidism may also predispose to the development of nephrocalcinosis, as hypercalciuria is typically more pronounced in patients with activating mutations of the calcium sensing receptor." (PMID 27384692, 2017). "To examine the PTH-independent effects of CaSR inhibition on renal calcium handling, we administered a calcilytic (CaSR antagonist) to individuals with post-surgical hypoparathyroidism (PSH)." (PMID 42183375, 2026). "Two of the 19 patients tested for anti-CaSR autoantibodies had detectable antibodies at baseline, and both had clinical hypoparathyroidism." (PMID 38605470, 2025). "The autoimmune nature of ICI-related hypoparathyroidism was based on finding activating calcium-sensing receptor (CaSR) autoantibodies in three cases." (PMID 36149449, 2022). "That is, they respond to pro-inflammatory cytokines by up-regulating the parathyroid calcium-sensing receptor (CaSR) with consequent development of hypocalcemic hypoparathyroidism and hypercalciuria." (PMID 36580074, 2022).
hypoparathyroidism (continued). "Of note, inflammatory cytokines, including IL-6, have been described to increase the parathyroid calcium-sensing receptor (CaSR), which reduces parathyroid hormone (PTH) secretion, resulting in inflammation-associated hypocalcemic hypoparathyroidism." (PMID 36233666, 2022). "As for idiopathic hypoparathyroidism and acute polyendocrine syndrome, CaSR-specific autoantibodies were identified in patient serum, implying a putative involvement of a CaSR-targeted autoimmunity in the etiology of those particular disorders." (PMID 36467702, 2022). "In order to investigate the reason for the hypoparathyroidism, we analyzed antibodies against the calcium sensing receptor (CaSR)." (PMID 30791949, 2019). "Interleukin-1β and IL-6 can increase bone resorption, thus releasing bone elements such as phosphate into the circulation, and can also upregulate the parathyroid CaSR, which will result in hypoparathyroidism and phosphate retention." (PMID 30071694, 2018). "Calcium metabolism is also disrupted as the patients develop hypocalcemic hypoparathyroidism likely due to an upregulation of the parathyroid calcium-sensing receptor, possibly due to inflammatory cytokine stimulation." (PMID 16921418, 2006). "Interestingly, all melanoma cases with ir-hypoparathyroidism had received nivolumab/ipilimumab; 3 of them were also screened and detected with positive calcium-sensing receptor (CaSR) antibodies." (PMID 40356787, 2025). "DNA analysis using a commercial next generation panel (Invitae hypoparathyroidism panel (PR06002.08)) revealed a heterozygous missense variant in the CASR gene (c.2168 T > G, p.Leu723Arg) that was not present in his parents." (PMID 39658204, 2025). "The patient we identified with the CaSR Arg723 variant had hypoparathyroidism and short stature, but growth defects are not common in individuals with activating CaSR mutations." (PMID 39658204, 2025). "The apparent coincidence of post-burn bone resorption and up-regulation of the CaSR in the sheep model suggested that the hypocalcemic hypoparathyroidism was protective against the influx of calcium from resorbing bone into the circulation, allowing the excretion of excess calcium." (PMID 36580074, 2022). "Cytokines, notably interleukin (IL)-1β and IL-6, lead to an upregulation of calcium-sensing receptor (CaSR) on parathyroid glands, increasing the sensitivity of the parathyroid cells to circulating calcium, resulting in a state of acquired relative hypoparathyroidism." (PMID 33490095, 2020). "However, attempts were performed to treat hypoparathyroidism and autosomal dominant hypocalcemia (ADH) driven by gain-of-function CaSR mutations with CaSR NAMs." (PMID 31719824, 2019). "One study focused on two large unrelated families counting a total of 15 living patients with autosomal dominant isolated hypoparathyroidism, in whom mutations in the genes encoding the CASR, PTH, and GCM2 were ruled out." (PMID 27803672, 2016). "While the upregulation of the calcium-sensing receptor may explain the hypocalcemia, hypercalciuria, and hypoparathyroidism we observe following burn injury, is there a way that these 2 phenomena may interact?" (PMID 16921418, 2006). "We molecularly diagnosed mutations in CASR, KMT2D, GNAS, PRKAR1A, and CYP27B1, corresponding to cases with clinical diagnoses of isolated hypoparathyroidism/primary hyperparathyroidism, syndromic hypoparathyroidism, pseudohypoparathyroidism, acrodysostosis, and calcipenic rickets." (PMID 41155848, 2025). "Greater than 90% of AIRE mutation-negative probands with suspected familial hypoparathyroidism had apparently isolated hypoparathyroidism, and around 30% of these probands were found to have an abnormality affecting either the CASR, GATA3, GCM2, GNA11 genes or the 22q11.2 chromosomal region." (PMID 35521792, 2022).